STAT3 (signal transducer and activator of transcription 3)
Diseases named in the same sentence as STAT3 in open-access papers (continued):
Sharing a sentence is not in itself a finding about the gene and the disease.
cancer (continued). "IL-6 has been seen to increase the oncogenic miR-21 levels through the STAT3 signaling pathway, which indicates that induction of miR-21 contributes to cancer progression through STAT3." (PMID 32679860, 2020). "Among the most well-known extracellular STAT3 activators are a large number of cytokines, chemokines and growth factors, as well as many tyrosine kinases that are upregulated in cancer." (PMID 33335857, 2020). "In this study, we sought to identify new druggable approaches to target STAT3 hyperactivity in cancers." (PMID 32231398, 2020). "Actually, STAT3 pathway was constitutively activated in cancer, and only after activation via phosphorylation, STAT3 was translocated to the nucleus and act as the oncogenic-associated protein." (PMID 32486001, 2020). "We suggest that STAT3 is one of the representative proteins that can shift the metabolic processes of cancer cells by exerting pro-oncogenic activity." (PMID 33003453, 2020). "Emerging evidence has shown that STAT3 is a key oncogenic factor involved in the activation of several pathways, including cell proliferation and invasion, as well as cancer cell survival." (PMID 33024090, 2020). "Flavonoids have been reported to induce apoptosis of human cancer cells, inhibit NF-κB and the IL-6/STAT3-mediated inflammatory signalling pathway, and also regulate levels of inflammatory cytokines such as IL-6, IL-1β, and TNF-α." (PMID 33082817, 2020). "STAT3 is one of the transcriptional factors that play an important role in cancer growth and proliferation." (PMID 32150979, 2020). "There are a wide variety of inhibitors of the JAK/STAT pathway; however, STAT3 is of greater importance in most cancers, which is why it has a more significant number of inhibitors undergoing clinical trials." (PMID 33076315, 2020). "Novel unpredicted interactions were found between leptin receptor, STAT3, and ABCB1, which has been linked to the development of drug resistance in cancer cells." (PMID 32471192, 2020). "We also found that STAT3 knockdown‐induced attenuation of cell proliferation resulted from cell death and cell cycle arrest, depending on cancer cell context." (PMID 32495998, 2020). "Gathered evidence suggests that STAT3 becomes hyperactivated not only in cancer cells themselves but also in immune cells and CAFs within the TME." (PMID 32972405, 2020). "This STAT3 pathway activation contributes to several characteristics, such as cancer proliferation, anti-apoptosis and angiogenesis, that favour carcinogenesis in the colon." (PMID 32863742, 2020). "STAT3 is one type of oncogene, which endorses cell survival, proliferation, motility, and progression in cancer cells." (PMID 32660101, 2020). "Mechanistically, these ADV-induced GSCs upregulated lncRNA NEAT1, which is downstream to TLR9 and plays important roles in cancer stem cells likely via strengthening STAT3." (PMID 32843056, 2020). "Reportedly, cryptotanshinone enhances the chemosensitivity of conventional chemotherapeutic drugs, such as doxorubicin and paclitaxel, in cancer cell lines by inhibiting the STAT3 signaling pathway." (PMID 32863764, 2020). "This activated STAT3 plays crucial roles in proliferation, survival, metastasis, and self-renewal of cancer cells." (PMID 31900385, 2020). "The levels of activated STAT3 have been shown to correlate with a poor clinical prognosis in several of these cancers." (PMID 32536866, 2020). "OLA1P2 upregulation markedly inhibits the nuclear transport of phosphorylated STAT3 by binding to and preventing homodimerization of phosphorylated STAT3, thus inhibiting STAT3 signaling and suppressing cancer progression." (PMID 35006436, 2020).
cancer (continued). "In line with this, the genes in the “IL6_JAK_STAT3_SIGNALING” and “TGF_BETA_SIGNALING” collections that are known to induce cancer cell metastasis were also depleted in the SH samples." (PMID 33343623, 2020). "Various studies have indicated that STAT-3 is a molecular target for curcumin via IL-6 modulation for various cancer types." (PMID 32806551, 2020). "The excessive activation of STAT3 signaling has been observed in many types of cancer, and is considered as one of the most frequent impact factors in cancer stemness maintenance." (PMID 31959918, 2020). "NDRG2 suppresses the invasion abilities of cancer cells through the inhibition of EGF-induced STAT3/Snail signaling by inhibiting the binding of STAT3 to the Snail promoter." (PMID 31952344, 2020). "Previous studies have provided evidence that indicates an association between aberrant phosphorylation of the transcription factor STAT3 and a wide variety of cancers." (PMID 32273843, 2020). "In both of these reports, the authors have shown that TLR9 participates in CSCs formation via STAT3, a multi-functional signal transduction molecule widely involved in stemness and cancer." (PMID 32843056, 2020). "AZD9150, a fabricated anti-sense oligonucleotide affecting STAT3 translation, has validated anti-cancer function in xenograft models." (PMID 35047986, 2020). "Abnormal activation of STAT3 is necessary for the survival of many human cancer cells, and inhibition of JAK2/STAT3 pathway by inhibitors or siRNAs can reduce cell survival and induce apoptosis." (PMID 32536869, 2020). "Peng and colleagues showed that MDSCs directly promoted and maintained cancer stemness through the interaction between IL6/STAT3 and the NO/NOTCH signaling pathway." (PMID 33091036, 2020). "Constitutive activation of STAT3 leading to cancer is the result of increased cytokine production (IL-6, IL-10), continuous cytokine receptor activation (VEGFR/EGFR), or non-receptor tyrosine kinases (JAKs, Src, Abl)." (PMID 33158194, 2020). "Given the oncogenic functions of STAT3, directly targeting STAT3 signaling represents a potential therapeutic approach to treating cancer." (PMID 32422984, 2020). "Here we showed that STAT3 signaling, one of the critical links between inflammation and cancer, acted as a control pathway in gastric carcinogenesis." (PMID 32041943, 2020). "The observed cytostatic effects are in agreement with previous studies showing that STAT3 can protect cancer cells from the apoptotic effects of many individual drugs: STAT3 activity controls the expression of pro-survival genes such as MCL1, BCL2 and BCL2L1." (PMID 32231398, 2020). "Until now, constitutive activation of STAT3 has been reported in numerous studies resulting into cancer proliferation, survival, progression and chemo-resistance." (PMID 33013353, 2020). "Cinobufagin was found to induce apoptosis in osteosarcoma cancer cells by suppressing cancer-promoting signaling pathways such as STAT3, Notch and NF-kB, and activating mitochondria-mediated apoptosis pathways." (PMID 32933177, 2020). "For instance, siRNAs can down-regulate expression of Bcl-2,STAT3, and elF5A2 to interfere with cancer cell proliferation." (PMID 33095554, 2020). "One possible explanation is the frequent activation of STAT3 in cancer by STAT3 protein phosphorylation." (PMID 32528731, 2020). "Combination groups significantly reduced the levels of p-STAT3 in two cancer cell lines compared with either chemical alone." (PMID 31948057, 2020). "Clinical trials have examined the relationship between STAT3 and the response of cancer cells to radiotherapy." (PMID 32545648, 2020).
cancer (continued). "Accumulating evidence has shown that signal transducer and activator of transcription 3 (STAT3) is constitutively activated and overexpressed in a variety of malignant tumours, including NSCLC." (PMID 32022328, 2020). "The enriched cancer hallmarks in low-risk group, including the interferon alpha (IFN-α) response, the interferon-γ (IFN-γ) response, IL-2/STAT5 signaling, IL-6/JAK/STAT3 signaling, epithelial mesenchymal transition, TGF-β signaling and hedgehog signaling." (PMID 32850356, 2020). "For example, STAT3 regulates pro-survival gene expression to increase apoptotic resistance in cancer." (PMID 32733808, 2020). "MSCs promotes the progression of gastric cancer cells through the release of CXCL16, which activates STAT3-mediated expression of Ror1 in the cancer cells." (PMID 33299638, 2020). "Here, using the microarray database, we explored the mRNA expression of STAT3 and found that STAT3 was significantly downregulated in various cancer samples compared with normal samples." (PMID 32486001, 2020). "Although both our results and other extensive research indicated that B7-H3 is able to activate the STAT3 pathway in multiple cancers, the precise way of B7H3 to regulate the STAT3 pathway is still unclear." (PMID 32127943, 2020). "NNMT is under the transcriptional control of STAT3, which is often overexpressed in various types of cancer." (PMID 33182817, 2020). "Janus Kinase (JAK)-Signal transducer and activator of transcription 3 (STAT3) pathway is vigorously triggered in multiple cancer types leading to cell survival, proliferation and resistance to the anticancer therapeutics." (PMID 33013353, 2020). "In this review, we summarize the functions and regulatory mechanism of STAT3 in cancer, and further explain the relationship between STAT3 activity and cancer metabolism in terms of oxidation regulation." (PMID 33003453, 2020). "The transcription factor STAT3 plays a key role in cancer and immunity, being widely explored as a potential drug target for the development of novel immunomodulatory or anticancer therapeutics." (PMID 32863208, 2020). "Recent studies revealed that the synthetic oxadiazoles possess STAT3 inhibitory activity in various preclinical cancer models." (PMID 32967366, 2020). "In this context, the synthesis and secretion of cytokines like interleukin-6 (IL-6), a potent STAT3 activator, have been reported in response to cytotoxic damage in cancer cells." (PMID 33023532, 2020). "Previous reports have shown that AKT acts upstream of STAT3 in some cancers, regulating cell viability, invasion, and migration." (PMID 32530437, 2020). "Co-culture of healthy monocytes with cancer cells or treatment with cancer cell-derived EVs induces STAT3 activation." (PMID 33042791, 2020). "During the last decade, several studies have shown that CD44 and STAT3 cooperate in cancer promotion." (PMID 33335857, 2020). "First, we demonstrated that the cancer-promoting actions of LINC00324 in RB cells were possibly mediated by the miR-769-5p–STAT3 axis." (PMID 32369777, 2020). "In cancer cells with a low Warburg effect, STAT3 is constitutively acetylated and localized to the mitochondria, where it maintains ATP synthesis in energy metabolism." (PMID 33003453, 2020). "STAT3 is a key regulator of metabolism in cancer progression, orchestrating cellular signalling pathways between the cytosol, nucleus and the mitochondria." (PMID 32731620, 2020). "The AKT/mTOR/STAT3 signaling pathway upregulated by radiation activates several epithelial‐mesenchymal transition transcription factors, including SNAI1, HIF‐1, ZEB1, and STAT3, thereby promoting cancer cell metastasis." (PMID 33344143, 2020). "On the other hand, stimulation of the STAT3 and NF-κB signaling pathways mediates the angiogenesis of cancer cells, and the inhibition of STAT3 can suppress migration." (PMID 32380783, 2020).
cancer (continued). "CXCR4-mediated STAT3 activation induces gefitinib-resistance and transition into stem-like cancer cells, which possess self-renewal capacity and radiation resistance." (PMID 31952344, 2020). "Previous reports have suggested that drug-resistant cancer cells show features of cancer stem-like cells (CSCs) and that STAT3 is one of the major factors contributing to CSC proliferation." (PMID 32724453, 2020). "STAT3, an important oncogene is widely reported in many malignant tumors, and its activation involved in the development and progression of GC6–8." (PMID 33082325, 2020). "STAT3 is persistently activated in numerous cancers and is involved in cancer cell proliferation, invasion, and migration." (PMID 32922496, 2020). "The STAT3 inhibitor TTI-101 is now undergoing testing in a Phase I clinical trial in patients with advanced cancers." (PMID 32823961, 2020). "Although the correlation between STAT3 and abundance of TIICs was verified in different cancer types, STAT3 was particularly correlated with the infiltrating level of neutrophil and DC." (PMID 32486001, 2020). "Benztropine also reduced the activity of oncogenic signaling transducers and trans-activators for MMP9, including STAT3, NF-κB, and β-catenin, and the properties of cancer stem cells/cancer-initiating cells." (PMID 32102440, 2020). "Here, we show that knockdown of STAT3 by siRNA treatment induces cell cycle arrest and apoptosis by a decrease in cap‐dependent translation in human cancer cells." (PMID 32495998, 2020). "Signal transducer and activator of transcription 3 (STAT3) is involved in many aspects of cancer adaptation to micro-environmental stress." (PMID 33182253, 2020). "Several researchers have found that IL11, another member of the IL6 family, can also activate JAK/STAT3 pathway in some cancer types 34-36." (PMID 33042272, 2020). "These correlations are mainly related to the functions of STAT3 in promoting the migration and invasion and maintaining stem cell properties of cancer cells, which indicates that STAT3 is an attractive molecular target for cancer therapy." (PMID 32183406, 2020). "As the first demonstration of UTMC-mediated delivery of STAT3 decoy to cancer cells of human origin, these data set the stage for clinical translation of ultrasound-mediated delivery of STAT3 decoy for the treatment of patients with head and neck tumors." (PMID 33206698, 2020). "For example, in all cell populations from cancer patients, there was a positive expression correlation between STAT3 and Akt." (PMID 33330068, 2020). "This review will discuss the role of the phytochemical targeting of STAT3 signalling-orchestrated lipid metabolism in improving therapeutic outcomes in cancer." (PMID 32731620, 2020). "Expression of cytokines in response to NF-κB results in activation of Stat3, which plays a key role in controlling communication between cancer cells and the surrounding microenvironment." (PMID 32317968, 2020). "STAT3 has been recognized as a transcription factor and oncogene in various cancers including the RCC." (PMID 32729669, 2020). "Recently, we found that the promoter region of miR-124, a putative regulator of STAT3 in different types of cancer, was robustly methylated in CTCL cell lines (including MF and SS) compared with inflammatory disease (ID) skin samples." (PMID 33333886, 2020). "An increasing body of evidence supports that the cytoplasmic TF STAT3 is activated constitutively in a variety of cancers wherein it significantly affects the growth of tumors and facilitates metastasis." (PMID 32812032, 2020). "Inhibition of MEK triggers the feedback activation of STAT3 that contributes to drug resistance in diverse oncogene-addicted cancer models." (PMID 31124056, 2020). "STAT3, which promotes cell proliferation of cancer cells, is one of the proteins that is activated in cellular signaling of immunosuppressive cytokines." (PMID 32488850, 2020).
cancer (continued). "STAT3 abnormal activation has been reported to be involved in the progression of several cancer types, including GBM." (PMID 32486489, 2020). "STAT3 inhibitors or STAT3-targeted oligonucleotide agents reduce the number and abolish the immunosuppressive activity of MDSCs in mouse models and cancer patients." (PMID 33081041, 2020). "These ILCs produce IL-22 that promotes cancer development by inducing epithelial cell proliferation through phosphorylation of the Stat3 pathway; neutralization of IL-22 leads to abrogation of this process." (PMID 32670290, 2020). "STAT3 is a transcription factor that regulates the expression of genes related to cell cycle, cell survival, and cancer malignancy." (PMID 32443845, 2020). "Persistent activation of STAT3 contributes to uncontrolled cell proliferation, angiogenesis, apoptotic resistance, and prosurvival effects in cancer cells." (PMID 33082325, 2020). "The concomitant activation of STAT3/5 by TKOs is probably the most intriguing event in leukemogenesis as both proteins in cancer cells have compensatory and/or opposing effects on gene expression and cell fate." (PMID 31963765, 2020). "Accumulating evidence suggests that TGFβ-stimulated CAFs increase the secretion of IL-6 and IL-11, which trigger GP130/STAT3 signaling in cancer cells and thus promote cancer metastasis and progression." (PMID 32972405, 2020). "The STAT3 decoy oligonucleotide binds to activated STAT3 with a high specificity and inhibits STAT3-mediated gene transcription and cancer cell proliferation." (PMID 33206698, 2020). "In particular, interleukin 6 (IL-6) and leptin, which are closely related to the mass of white adipose tissue (WAT), are known to activate STAT3 in cancer cells or tissues." (PMID 32722030, 2020). "In conclusion, the role of STAT3 in the radio-response of cancer has been paid more and more attention to." (PMID 32733808, 2020). "In GBM, the proinflammatory cytokines IL-17 and IL-22 have been identified as cancer-promoting molecules activating oncogenic STAT3 signaling, thereby protecting GBM cells from apoptosis, promoting GBM proliferation and enhancing invasion." (PMID 32069807, 2020). "The hallmarks of cancer coordinated by the STAT3-dependent transcriptional regulation of target proteins directly underpin the cellular responses." (PMID 31952344, 2020). "In this review, we discuss some new insights into the effect of STAT3 and its subtype STAT3β on chemoradiotherapy sensitivity, and we explore how these insights influence clinical treatment and drug development for cancer." (PMID 32872659, 2020). "For example, phosphorylated-STAT3 expression seemed to be higher in CD45+ cells in cancer samples than in CIN3 biopsies, which would correlate with the pattern observed in blood samples." (PMID 33330068, 2020). "Abnormal stimulation of STAT-3 in various cancerous cells led to the developmentof STAT-3 inhibitors as an anti-cancer defense." (PMID 32167126, 2020). "The mechanisms by which STAT3 can be constantly activated in the glycolysis process of cancer cells have been comprehensively proposed." (PMID 33003453, 2020). "EGCG plays an important role in cancer prevention by inhibiting the activity of Signal Transducer and Activator of Transcription 3 (STAT3)." (PMID 32660101, 2020). "It has been demonstrated that IL-6 can induce STAT3 to ensure the malignant behavior of cancer cells." (PMID 32545648, 2020). "In many types of cancers STAT3 is constitutively activated and STAT3 inhibitors have shown promise as antitumour therapies, however, few have entered clinical trials due to a lack of efficacy as a result of adverse side effects and toxicity." (PMID 32731620, 2020). "Our data showed that curcumin synergistically potentiated the chemotherapeutic potential of cisplatin, as it enhanced reduction in cell viability, proliferation, and apoptosis through the downregulation of JAK/STAT3-mediated cancer stemness." (PMID 31936675, 2020).